CX3CL1 (C-X3-C motif chemokine ligand 1)
Diseases named in the same sentence as CX3CL1 in open-access papers (continued):
Sharing a sentence is not in itself a finding about the gene and the disease.
Sepsis (16 papers, 2015 to 2025). Sepsis is defined as life-threatening organ dysfunction caused by a dysregulated host response to infection. "Importantly, two studies showed that the rs12692386 A > G allele of ADAM17 increased the protease expression and shedding of TNF, IL-6R, and CX3CL1, conferring a higher risk of severe disease and shock in sepsis." (PMID 38881671, 2024). "Endogenous CX3CL1 falls during a rat model of sepsis and is associated with lower MFG-E8." (PMID 30886578, 2019). "Moreover, low CX3CR1 is associated with marked neuronal loss after systemic inflammation and facilitates sepsis-induced immunosuppression resulting from monocyte inability to recognize CX3CL1 and kill pathogenic microorganisms." (PMID 28096568, 2016). "In a study using a mouse model of CLP-induced sepsis, CX3CL1 treatment increased mortality and inflammatory cytokines." (PMID 40508161, 2025). "In studies using serum from patients admitted to intensive care units (ICU) with sepsis, serum CX3CL1 was significantly higher in septic patients than in healthy patients." (PMID 40508161, 2025). "The involvement of CX3CL1/CX3CR1 axis in sepsis, therefore, has been reported conflictingly and requires further investigation." (PMID 40508161, 2025). "Recent research indicates that administering CX3CL1 can modulate the inflammatory response in mice with sepsis." (PMID 39763654, 2024). "CX3CR1’s interaction with its ligand, CX3CL1, has been acknowledged since 2008, where it was shown to facilitate the arrest and migration of pro-inflammatory cells during sepsis progression." (PMID 38263335, 2024). "The level of soluble CX3CL1 is correlated with disease severity and clinical outcomes in patients with sepsis." (PMID 35563195, 2022). "Among the three patient subgroups, the severe sepsis patients displayed the highest CX3CL1 expression level, whereas the sepsis subtype patients displayed the lowest expression of TNF-a, IL-6 and IL-1β." (PMID 25888255, 2015). "We found that the severe sepsis patients expressed significantly higher levels of CX3CL1, IL-6R, and TNF-a than the healthy controls." (PMID 25888255, 2015). "This suggested that CX3CL1 may exacerbate sepsis by increasing inflammation and decreasing bacterial clearance." (PMID 40508161, 2025). "Furthermore, serum concentrations of CX3CL1 were significantly correlated with the number of sepsis survivors." (PMID 40508161, 2025). "The expression of CX3CL1 is a potential biomarker for sepsis." (PMID 35563195, 2022). "The authors found MFG-E8 can be rescued by injecting CX3CL1, which also improves the sepsis." (PMID 30886578, 2019). "Importantly, we found that among the subgroup of patients with severe sepsis, the rs653765 CC genotype carriers expressed significantly higher levels of CX3CL1, IL-6R and TNF-a than the CT/TT carriers." (PMID 25888255, 2015). "However, less is known how these serum inflammatory markers might be related to gut microbiota, although serum CX3CL1 has been related to bacterial clearance in sepsis." (PMID 37237391, 2023). "Furthermore, Friggeri and colleagues showed that the level of Cx3cl1 expression was inversely proportional to mortality in patients with sepsis, suggesting that this chemokine has an important role in the severity of sepsis and mortality." (PMID 34421366, 2021). "Moreover, the rs653765 CC genotype in severe sepsis showed a higher ADAM10 level compared to healthy groups, and the rs653765 CC polymorphism had a strong impact on the production of the ADAM10 substrates CX3CL1, IL-6R and TNF-α." (PMID 25888255, 2015). "Among the molecular variables, IL-1Ra, IL-17A, CCL19, CX3CL1 and TNF were significantly higher in septic patients compared to the infection non-sepsis group." (PMID 37691028, 2023). "In the clinical setting, CX3CL1 and MFG-E8 play an important role during the resolution phase of acute lung injury or sepsis." (PMID 34685562, 2021).
Sepsis (continued). "Our results indicated that the expression of CX3CL1, IL-6R, TNF-a, IL-1ß and IL-6 were significantly higher in the sepsis patients (subtype) than in the healthy controls." (PMID 25888255, 2015). "The differences in the expression levels of ADAM10 substrates (CX3CL1, IL-6R and TNF-a) and the pro-inflammatory cytokines IL-1ß and IL-6 according to the ADAM10 genotype were analyzed in PBMCs from the sepsis patients and the controls." (PMID 25888255, 2015). "As sepsis is a systemic intravascular infectious disease, during sepsis, the endothelial cells in the cerebrovascular blood vessels also produce various chemokines, such as CCL2, CCL3, CCL5, CXCL1, CXCL2, CX3CL1, and CXCL8." (PMID 38585633, 2024). "Additionally, the plasma levels of IL-1Ra, IL-17A, CCL19, CX3CL1, and TNF were significantly higher in septic patients compared to the non-sepsis group." (PMID 37691028, 2023).
melanoma (15 papers, 2011 to 2025). A malignant, usually aggressive tumor composed of atypical, neoplastic melanocytes. "For instance, in melanoma, high expression of CX3CL1 was associated with a better prognosis after immunotherapy." (PMID 36397015, 2022). "Of these, the mRNA expression of THBS1 and THBS2 has been inversely associated with melanoma growth and progression, while CX3CL1 inhibition has been shown to reduce melanoma growth and angiogenesis in mice." (PMID 21615965, 2011). "Our data demonstrate the direct transcriptional regulation of CX3CL1 by GLI1 in melanoma cells, consistent with a recent study." (PMID 39090759, 2024). "We found that the presence of the receptor of CX3CL1, CX3CR1, was associated with a significantly higher five-year survival of melanoma patients (log-rank Mantel-Cox test, p = 0.04)." (PMID 39011040, 2024). "As in all cancers, CX3CL1 (higher levels in melanoma and renal cancer), TNFβ, VEGF and IL-1RA showed the greatest variability of cytokines and chemokines expressed in the < 10.0 pM range." (PMID 39114667, 2024). "Significantly higher levels of Ifng, Nos2, Il12, Ccl5, Cx3cl1, and Cxcl9 — and, by contrast, significantly lower levels of Arg1 — were detected in the melanomas of Colec11–/– mice, compared with WT mice." (PMID 36883567, 2023). "The finding that the blockade of CX3CL1 reverts the increase in PMN-MDSC proliferation and invasion induced by GLI1, suggests that this phenotype could be mediated by increased expression and secretion of CX3CL1 by melanoma cells." (PMID 39090759, 2024). "In this study, using a preclinical model of melanoma that lacks CX3CL1 expression and tumor-specific CD8+ T cells in which the CX3CR1 gene was replaced with a functionally unrelated gene, we have demonstrated the intratumoral generation of antigen-specific CX3CR1+ CD8+ T cells." (PMID 38881188, 2024). "Indeed, a previous study showed that enhanced expression of CX3CL1 in the tumor improves control of the established tumor in multiple preclinical models, including B16 melanoma, by NK-cell– and T-cell–dependent mechanisms." (PMID 38881188, 2024). "Furthermore, thorough analysis of the TCGA-SKCM public dataset from 98 melanoma patients revealed the role of CX3CL1 and its receptor CX3CR1 in melanoma patients." (PMID 39011040, 2024). "In this regard, we confirmed the presence of CX3CL1 in melanoma tumours." (PMID 38903497, 2024). "Therefore, we hypothesize that mutations in CX3CL1 may also impact the function of ICAM-1, thereby influencing melanoma cell proliferation, invasion, and angiogenesis; however further in vitro experiments are required." (PMID 37875556, 2023). "In our study, CX3CL1 was released exclusively during apoptotic cell death induced by MTX in murine fibrosarcoma MCA205 and melanoma B16-F10 cells." (PMID 39011040, 2024). "For example, on an experimental murine carcinogenesis model using several cancerous cell lines from different origins (colon, melanoma, LLC), the effect of DCs overexpressing CX3CL1 (DC-CX3CL1) on pre-existent tumors was examined." (PMID 33391453, 2021). "GLI1 overexpression in human melanoma A375 cells, which express low level of GLI1, increased CX3CL1 mRNA expression, suggesting a direct transcriptional regulation of CX3CL1 by GLI1." (PMID 39090759, 2024). "In this study, we assessed the secretion of CX3CL1 from MTX-treated murine fibrosarcoma MC205 and melanoma B16-F10 cells undergoing immunogenic apoptosis (i.e., apoptotic cell death exhibiting ICD characteristics), and explored its potential as a mediator of anti-tumour immunity during ICD." (PMID 39011040, 2024). "While this suggests that some of these recruited monocytes may gain CD16 expression as they differentiate within tumours, we cannot rule out the possibility of the direct recruitment of the non-classical CD16+ monocytes into the tumours, likely via CX3CL1 available in the melanoma TME." (PMID 38903497, 2024).
melanoma (continued). "Overall, 89%, 92%, 82%, and 50% of patients failed to display detectable serum levels of BAFF/TNFSF13B, CX3CL1, LTα, and CCL21 (defined as < 2 pg/ml, < 0.5 pg/ml, < 1 pg/ml and <7 pg/ml for the respective analytes) amongst an initial cohort of 78 melanoma patients evaluated." (PMID 37435077, 2023).
multiple sclerosis (15 papers, 2012 to 2025). A progressive autoimmune disorder affecting the central nervous system resulting in demyelination. "Consistent with this, in the course of multiple sclerosis, one of the polymorphic variants of CX3CR1, namely, CX3CR1I249/T280, affects the affinity of CX3CL1 for its receptor and the expression of the receptor itself." (PMID 39062768, 2024). "An animal model of experimentally induced autoimmune encephalomyelitis represents a disease closely related to multiple sclerosis, in which the expression of CX3CL1 and CX3CR1 changes within the sites of demyelination." (PMID 39062768, 2024). "In models of Alzheimer’s disease (AD), multiple sclerosis (MS) and neurotoxin models of PD, the chemokine CX3CL1 (fractalkine) and its receptor (CX3CR1) have important roles in modulating neuroinflammation." (PMID 26469270, 2015). "Furthermore, pain-mediated neuronal signaling and neuroinflammation were ameliorated by CX3CL1 neutralizing Ab administration in multiple sclerosis and hepatic encephalopathy models." (PMID 33858422, 2021). "Notably, microglia may upregulate the CX3CL1/CX3CR1 axis to autoregulate overactivation in pathological conditions like multiple sclerosis." (PMID 40822679, 2025). "Although the relationship between soluble CX3CL1 in peripheral blood and inflammatory diseases of the CNS has not been studied, serum CX3CL1 is increased in patients with multiple sclerosis, TBI and HIV with CNS complications." (PMID 25635231, 2014). "Additionally, the CX3CL1/CX3CR1 axis may switch microglia to a neuroprotective type with enhanced phagocytic activity and promote myelin debris clearance and remyelination in multiple sclerosis." (PMID 29311834, 2017).
ovarian carcinoma (15 papers, 2011 to 2026). A malignant neoplasm originating from the surface ovarian epithelium. "The mechanism by which CX3CL1 gene polymorphisms affect the clinical efficacy of carboplatin in patients with ovarian cancer needs to be explored by large-scale, multicenter studies." (PMID 36685881, 2022). "Collectively, we demonstrated that the clinical efficacy of carboplatin in ovarian cancer patients was associated with polymorphisms of CX3CL1 [rs223815 (G>C) and rs682082 (G>A)]." (PMID 36685881, 2022). "In a follow-up study, we will add more toxicity indicators of chemotherapy drugs to comprehensively evaluate the effect of CX3CL1/CX3CR1 gene polymorphisms on the clinical efficacy of carboplatin in patients with ovarian cancer." (PMID 36685881, 2022). "Genotypes and allele frequency of CX3CL1/CX3CR1 SNPs in carboplatin-treated ovarian cancer patients (n = 127)." (PMID 36685881, 2022). "In this study, we selected ovarian cancer patients who were treated in our hospital from January to December 2020 to conduct relevant clinical trials to explore the clinical efficacy of CX3CL1/CX3CR1 gene polymorphisms in carboplatin-treated patients." (PMID 36685881, 2022). "Nevertheless, loss of CX3CL1 expression in the fallopian carcinoma revealed in this study, which remains expressed in ovarian carcinoma, suggests dissimilar gene expression patterns between these two malignancies." (PMID 26633537, 2015). "Thus, in contrast to its favourable prognostic role in other cancer entities and in contrast to the positive prognostic impact of other T-cell and NK cell recruiting chemokines (e.g. CXCL9 and CXCL10) in ovarian cancer, elevated CX3CL1 levels are associated with worsened outcome in HGSOC." (PMID 39862711, 2025). "Functional effects of CX3CL1 on ovarian cancer cells were evaluated via migration and proliferation assays in the murine ID8 cell line." (PMID 42279436, 2026). "In summary, both membrane-bound and soluble isoforms of CX3CL1 are expressed by human and murine ovarian carcinoma cells." (PMID 39862711, 2025). "Having detected CX3CL1 expression by immunohistochemistry in tumour cells from HGSOC patients, we next sought to confirm its expression and also the regulation of CX3CL1 in ovarian cancer cells in vitro." (PMID 39862711, 2025). "In preclinical ovarian cancer, CX3CL1 plays a dual role, as it enhances the adaptive anti-tumour response, but overall still promotes tumour growth, the latter as a feature of the intraperitoneal environment." (PMID 39862711, 2025). "Next, 1×107 Ctrl or Cx3cl1+ cells were intraperitoneally implanted into C57BL/6 mice in which they mimicked the metastatic pattern of advanced human ovarian cancer (ascites formation, tumour outgrow in the mesentery and the diaphragm)." (PMID 39862711, 2025). "Our observation that PARP inhibitors are able to induce CX3CL1 independently of the presence of inflammatory cytokines in ovarian cancer cell lines provides a first indication that this chemokine system can be modulated by contemporary therapies." (PMID 39862711, 2025). "Taken together, we show in the present study that CX3CL1, despite activating the adaptive anti-tumour response in ovarian cancer, has an overall tumour-promoting function, which is due in particular to the peculiarities of the intraperitoneal milieu." (PMID 39862711, 2025). "For instance, CX3CR1 was significantly correlated with CCL2/3 and (R = 0.34, P < 1.03e−09) and CX3CL1 (R = 0.18, P < .0015) in epithelial ovarian cancer." (PMID 38241595, 2024). "CX3CR1 was also found to be expressed in more than 64% of metastatic ovarian cancer specimens, and it promotes ovarian cancer cell adhesion to the mesothelial monolayer and proliferation in a CX3CL1-dependent manner." (PMID 36685881, 2022).
ovarian carcinoma (continued). "We examined a total of 22 genotypes of CX3CL1 and CX3CR1 to explore the association between different genotypes and the clinical efficacy of carboplatin treatment in ovarian cancer patients." (PMID 36685881, 2022). "Association of CX3CL1 and CX3CR1 SNPs with the clinical efficacy of carboplatin treatment in ovarian cancer patients." (PMID 36685881, 2022). "Based on this, in-depth exploration of the function and mechanism of the CX3CL1/CX3CR1 axis in ovarian cancer will provide a strong theoretical basis for the targeted therapy of ovarian cancer." (PMID 36685881, 2022). "We also found that STK3 promoted the recruitment of CD8+ T-cells via an increase in chemokine CXCL16 and CX3CL1 production in human ovarian cancer cells." (PMID 33062724, 2020). "Our previous studies demonstrated that interaction of CX3CR1 expressed in ovarian carcinoma cells with membrane-tethered CX3CL1 expressed in peritoneal mesothelial cells mediates peritoneal adhesion of disseminating cells." (PMID 29712888, 2018). "We and others have shown that secreted CX3CL1 facilitates ovarian cancer cell proliferation and migration in vitro." (PMID 29712888, 2018). "The chemokine (C-X3-C motif) receptor 1 (CX3CR1) is expressed by ovarian cancer cells and was shown to mediate in vitro tumour cell adhesion to mesothelial cells by interacting with mesothelial chemokine (C-X3-C motif) ligand 1 (CX3CL1)." (PMID 27074785, 2016). "Patterns of CX3CR1 and CX3CL1 expression in normal epithelium of ovary and fallopian tube, fallopian epithelium with chronic inflammation, ovarian carcinoma, and fallopian adenocarcinoma." (PMID 26633537, 2015). "This is opposite from the ovarian carcinoma, where both CX3CR1 and CX3CL1 are expressed by the ovarian carcinoma cells." (PMID 26633537, 2015). "CX3CL1 expression has been previously reported in normal and pathologic ovarian surface epithelium, ovarian carcinoma, and normal fallopian tube epithelium." (PMID 26633537, 2015). "Collectively, our study shows that CX3CL1 is a driver of intraperitoneal tumour growth in ovarian cancer, a feature that may compromise the anticancer effect of CX3CL1-inducing PARP inhibitors." (PMID 39862711, 2025). "We also cannot confirm an increased proliferation of tumour cells by CX3CL1 overexpression, as has been demonstrated in the ovarian carcinoma cell line BG-1, either in the growth curves in vitro or by proliferation markers such as Ki67 in vivo, and therefore it does not appear to be causative." (PMID 39862711, 2025). "The results showed that the CX3CL1 genotypes rs223815 (χ2 = 6.592, p = 0.037) and rs682082 (χ2 = 7.025, p = 0.030) were closely related to the clinical efficacy of carboplatin treatment for ovarian cancer." (PMID 36685881, 2022). "For example, CX3CL1 as a chemokine has been associated with better patient outcomes by recruiting NK and CD8+ T cells in gastric adenocarcinoma; paradoxically, CX3CL1 was also found to stimulate the proliferation of gastric and ovarian cancer cells by activating EGFR." (PMID 36397015, 2022). "At present, studies have reported that the CX3CL1/CX3CR1 biological axis can affect the drug resistance of ovarian cancer cells by mediating changes in the levels of inflammatory factors and cytokines, thereby maintaining the sensitivity of tumor cells to platinum drugs." (PMID 36685881, 2022). "As research continues to advance, the role of the CX3CL1/CX3CR1 biological axis in tumors is gradually being explored, but the roles of their gene polymorphisms in ovarian cancer are relatively unknown and require more exploration." (PMID 36685881, 2022). "However, CX3CL1 is expressed only by ovarian carcinoma, and its expression is lost in fallopian carcinoma." (PMID 26633537, 2015). "Finally, we show that PARP inhibitors can induce CX3CL1 in ovarian cancer cells, which could compromise their therapeutic efficacy." (PMID 39862711, 2025).